OSCP1 (organic solute carrier partner 1)
Description:
May be involved in drug clearance in the placenta.
Synonyms: C1orf102; NOR1
Tractability: Antibody: UniProt places it where antibodies can reach, with medium confidence; its Gene Ontology location is reachable by antibodies, with medium confidence. PROTAC: its protein half-life has been measured.
Gene: Protein-coding gene on chromosome 1 (36,415,827 to 36,450,451, reverse strand). Ensembl gene ENSG00000116885.
Subcellular location: Basal cell membrane
Gene Ontology:
Molecular function: transmembrane transporter activity
Biological process: xenobiotic detoxification by transmembrane export across the plasma membrane
Cellular component: basal plasma membrane; cytoplasm; plasma membrane
Genetic constraint (gnomAD): Loss-of-function variants: 34 observed, 46.67 expected, observed/expected ratio (o/e) 0.73, 90% interval 0.55 to 0.97. The upper end of that interval is the gene's LOEUF score, 0.97, which puts it in group 4 of 6, group 1 being the genes least tolerant of losing a copy. Missense variants: 391 observed, 477.44 expected, observed/expected ratio (o/e) 0.82, 90% interval 0.75 to 0.89. Synonymous variants: 177 observed, 184.92 expected, observed/expected ratio (o/e) 0.96, 90% interval 0.85 to 1.08.
Homologues: Orthologues: macaque OSCP1 (98% identical), chimpanzee OSCP1 (95% identical), dog OSCP1 (92% identical), guinea pig OSCP1 (92% identical), pig OSCP1 (90% identical), rat Oscp1 (89% identical), mouse Oscp1 (87% identical), rabbit OSCP1 (81% identical), tropical clawed frog oscp1 (77% identical), zebrafish OSCP1 (75% identical), zebrafish oscp1a (58% identical), Drosophila melanogaster OSCP1 (24% identical), and 1 more.
Diseases named in the same sentence as OSCP1 in open-access papers:
OSCP1 is named in the same sentence as 8 diseases in open-access papers, as found by Europe PMC text mining. Sharing a sentence is not in itself a finding about the gene and the disease. The quoted sentences say what the papers report.
nasopharyngeal carcinoma (4 papers, 2011 to 2019). A carcinoma arising from the nasopharyngeal epithelium. "OSCP1 was first implicated as a tumor suppressor in nasopharyngeal cancer and later found to modulate transport rates of organic solutes over the plasma membrane in rodents." (PMID 31095607, 2019). "Aberrant methylation of OSCP1 has been shown in nasopharyngeal carcinoma and acute myeloid leukemia." (PMID 21760961, 2011). "Moreover, OSCP1 is known as a tumor suppressor gene that is frequently down-expressed in nasopharyngeal carcinomas and acute myeloid leukemia." (PMID 24939707, 2014). "Therefore, connecting OSCP1 to the cilium might provide the missing link to connect previously observed effects of OSCP1 on organic solute in-/efflux and its role in nasopharyngeal cancer." (PMID 31095607, 2019).
ciliopathy (1 paper, 2019). A genetic disorder of the cellular cilia or the cilia anchoring structures, the basal bodies, or of ciliary function. "For example, we show that OSCP1, which has previously been implicated in two distinct non-ciliary processes, causes ciliogenic and ciliopathy-associated tissue phenotypes when depleted in zebrafish." (PMID 31095607, 2019).
leukemia (1 paper, 2011). A malignant (clonal) hematologic disorder, involving hematopoietic stem cells and characterized by the presence of primitive or atypical myeloid or lymphoid cells in the bone marrow and the blood. "DPYS, NPM2, OSCP1, PDLIM4 and TFAP2E genes were found hypermethylated, and CDKN2B (p15INK4B) homozygously deleted in the K562 leukemia cell line." (PMID 21760961, 2011).
uterine cervix cancer (1 paper, 2020). "SNORD3A and its host genes OSCP1 were found down-regulated in uterine cervix cancer, although the biological and clinical meaning of this change has not been investigated." (PMID 32599901, 2020).
tumor (6 papers, 2014 to 2023). "In-depth analysis of the DEGs that exhibited significant changes in K562 cells treated with WIP2W showed an elevation of tumor suppressor genes, including OSCP1, and genes related to cell apoptosis such as FXYD6, NPTX1, and GPR142." (PMID 37765274, 2023). "SNORD3A helps the processing of rRNA and its host gene OSCP1 is a tumor suppressor gene." (PMID 32599901, 2020). "Among these 20 common genes, the expression levels of CDK20, AKAP7, AZIN2, LIX1L, OSCP1, and SLFN12 were upregulated, while HLF was downregulated in TC-PD-L1+ tumours (Pattern 3 and Pattern 4)." (PMID 29921949, 2018).
OSCP1 also shares sentences with these, for which no sentence is quoted: acute myeloid leukemia (2 papers); hepatocellular carcinoma (2); carcinoma (1).